CCDC140 (CCDC140 long non-coding RNA)
Synonyms: FLJ32447
Gene: Long non-coding RNA gene on chromosome 2 (222,298,147 to 222,305,217, forward strand). Ensembl gene ENSG00000163081.
Diseases named in the same sentence as CCDC140 in open-access papers:
CCDC140 is named in the same sentence as 6 diseases in open-access papers, as found by Europe PMC text mining. Sharing a sentence is not in itself a finding about the gene and the disease. The quoted sentences say what the papers report.
lung adenocarcinoma (1 paper, 2025). A carcinoma that arises from the lung and is characterized by the presence of malignant glandular epithelial cells. "The analysis revealed that promoter methylation levels of CCDC140 in both lung adenocarcinoma (LUAD, n= 449) and lung squamous cell carcinoma (LUSC, n = 370) were significantly higher than those in adjacent normal lung tissues (n = 68)." (PMID 41404798, 2025).
pancreatic cancer (1 paper, 2025). "Low-level methylation was also detected in the adjacent tissues, indicating that CCDC140 methylation is closely associated with pancreatic cancer." (PMID 41404798, 2025). "ddPCR also showed significantly higher CCDC140 methylation in pancreatic cancer tissues compared to the corresponding adjacent non-tumor tissues." (PMID 41404798, 2025).
CCDC140 also shares sentences with these, for which no sentence is quoted: cancer (1 paper); lung squamous cell carcinoma (1); osteosarcoma (1); tumor (1).